NAPA-AS1 (NAPA antisense RNA 1)
Gene: Long non-coding RNA gene on chromosome 19 (47,484,282 to 47,502,399, forward strand). Ensembl gene ENSG00000268061.
Diseases named in the same sentence as NAPA-AS1 in open-access papers:
NAPA-AS1 is named in the same sentence as 1 disease in open-access papers, as found by Europe PMC text mining. Sharing a sentence is not in itself a finding about the gene and the disease. The quoted sentences say what the papers report.
ischemic stroke (1 paper, 2021). A stroke disorder caused by obstruction of blood flow to the brain, due to thrombotic (local blood clot formation) or embolic (due to a blood clot or other material traveling from another site) event. "Regulatory axis, such as SND1-IT1/NAPA-AS1/LINC01001-miR-24-3p-LPAR3/ADORA1 and LUCAT1/ASAP1-IT2-miR-93-3p-GPR17 may play important roles in the progression of ischemic stroke." (PMID 34483854, 2021). "lncRNA-miRNA-mRNA regulatory axis such as SND1-IT1/NAPA-AS1/LINC01001-miR-24-3p-LPAR3/ADORA1 and LUCAT1/ASAP1-IT2-miR-93-3p-GPR17 may play important roles in the progression of ischemic stroke." (PMID 34483854, 2021).